SLC18A3 (solute carrier family 18 member A3)
Description:
Electrogenic antiporter that exchanges one cholinergic neurotransmitter, acetylcholine or choline, with two intravesicular protons across the membrane of synaptic vesicles. Uses the electrochemical proton gradient established by the V-type proton-pump ATPase to store neurotransmitters inside the vesicles prior to their release via exocytosis (By similarity). Determines cholinergic vesicular quantal size at presynaptic nerve terminals in developing neuro-muscular junctions with an impact on motor neuron differentiation and innervation pattern (By similarity). Part of forebrain cholinergic system, regulates hippocampal synapse transmissions that underlie spatial memory formation (By similarity). Can transport serotonin.
Synonyms: VAChT; CMS21
Tractability: Small molecule: a structure with a bound ligand is known; a high-quality ligand is known; it belongs to a druggable protein family. Antibody: its Gene Ontology location is reachable by antibodies, with high confidence; UniProt predicts a signal peptide or a membrane-spanning region. PROTAC: a small molecule that binds it is known.
Target class: Electrochemical transporter; SLC18 family of vesicular amine transporters; Transporter; SLC superfamily of solute carriers
Gene: Protein-coding gene on chromosome 10 (49,610,310 to 49,612,720, forward strand). Ensembl gene ENSG00000187714.
Subcellular location: Cytoplasmic vesicle, secretory vesicle, synaptic vesicle membrane
Pathways (Reactome):
Vesicle-mediated transport: Cargo recognition for clathrin-mediated endocytosis; Clathrin-mediated endocytosis
Neuronal System: Acetylcholine Neurotransmitter Release Cycle
Gene Ontology:
Molecular function: acetylcholine:proton antiporter activity; monoamine:proton antiporter activity; protein binding; acetylcholine transmembrane transporter activity; transmembrane transporter activity
Biological process: acetylcholine uptake; serotonin uptake; chemical synaptic transmission; neurotransmitter transport; positive regulation of acetylcholine secretion, neurotransmission; positive regulation of long-term synaptic potentiation; positive regulation of neuromuscular junction development; proton transmembrane transport; transmembrane transport
Cellular component: AP-1 adaptor complex; AP-2 adaptor complex; clathrin-coated endocytic vesicle membrane; clathrin-sculpted acetylcholine transport vesicle membrane; plasma membrane; terminal bouton; synaptic vesicle membrane
Genetic constraint (gnomAD): Loss-of-function variants: 21 observed, 24.94 expected, observed/expected ratio (o/e) 0.84, 90% interval 0.6 to 1.21. The upper end of that interval is the gene's LOEUF score, 1.21, which puts it in group 5 of 6, group 1 being the genes least tolerant of losing a copy. Missense variants: 744 observed, 751.27 expected, observed/expected ratio (o/e) 0.99, 90% interval 0.93 to 1.05. Synonymous variants: 415 observed, 357.15 expected, observed/expected ratio (o/e) 1.16, 90% interval 1.07 to 1.26.
Homologues: Orthologues: chimpanzee SLC18A3 (99% identical), macaque SLC18A3 (98% identical), mouse Slc18a3 (94% identical), rabbit SLC18A3 (93% identical), guinea pig SLC18A3 (91% identical), pig SLC18A3 (88% identical), dog SLC18A3 (87% identical), tropical clawed frog slc18a3 (66% identical), zebrafish slc18a3a (66% identical), zebrafish slc18a3b (56% identical), Drosophila melanogaster VAChT (49% identical), Caenorhabditis elegans unc-17 (45% identical). Paralogues in human: SLC18A1 (36% identical), SLC18A2 (34% identical), SLC18B1 (17% identical).
Diseases named in the same sentence as SLC18A3 in open-access papers:
SLC18A3 is named in the same sentence as 69 diseases in open-access papers, as found by Europe PMC text mining. Sharing a sentence is not in itself a finding about the gene and the disease. The quoted sentences say what the papers report.
cognitive deficits (7 papers, 2017 to 2025). "Nevertheless, the observation of intrauterine death in a SLC18A3 patient with a homozygous nonsense variant (c.1116C>A, p.Cys372*) accords with lethality of homozygous VAChT knock-out, whereas animals with a 70% reduction of expression levels of VAChT are myasthenic and have cognitive deficits." (PMID 34943989, 2021).
congenital myasthenic syndrome (3 papers, 2019 to 2025). Congenital myasthenic syndrome (CMS) is a group of genetic disorders of impaired neuromuscular transmission at the motor endplate characterized by fatigable muscle weakness. "Lipid accumulation in muscle fibers is known to be associated with muscle denervation and atrophy in relation to myosteatosis and has recently also been described in the context of SLC18A3-related congenital myasthenic syndrome, a NMJ disorder." (PMID 41464539, 2025).
Brain atrophy (2 papers, 2020 to 2021). Partial or complete wasting (loss) of brain tissue that was once present. "Two SLC18A3 patients showed brain atrophy (Patients 1 and 6), both presenting apnoea neonatally as well." (PMID 34943989, 2021).
Cerebral atrophy (1 paper, 2019). Atrophy (wasting, decrease in size of cells or tissue) affecting the cerebrum. "Recently, mutations in the SLC18A3 gene have been shown to manifest as neurodevelopmental delay with cerebral atrophy." (PMID 30808424, 2019).
Respiratory insufficiency (1 paper, 2021). "The majority of SLC18A3 patients already showed onset of their symptoms neonatally, only one patient during infancy, with respiratory insufficiency, bulbar symptoms or apnoea as the dominating symptoms at disease onset." (PMID 34943989, 2021).
SLC18A3 also shares sentences with these, for which no sentence is quoted: Parkinson disease (9 papers); Alzheimer disease (7); Anxiety (7); tumor (7); depression (6); dementia (5); Hypertension (5); Obesity (5); diabetes (4); inflammation (4); breast carcinoma (3); Huntington disease (3); memory impairment (3); prostate carcinoma (3); schizophrenia (3); Arrhythmia (2); brain diseases (2); cancer (2); cognitive decline (2); cystitis (2); Dystonia (2); epilepsy (2); intellectual disabilities (2); myasthenia (2); neurodegenerative disease (2); Parkinson (2); acute endometritis (1); airway hyperresponsiveness (1); asthma (1); bronchioalveolar carcinoma (1).
A further 34 diseases each share a sentence with SLC18A3 in 1 paper.